AR (androgen receptor)
Diseases named in the same sentence as AR in open-access papers (continued):
Sharing a sentence is not in itself a finding about the gene and the disease.
prostate tumors (continued). "Despite this heterogeneity, prostate tumor growth is, almost always, dependent upon the androgen receptor (AR) pathway, explaining the efficacy of androgen deprivation therapies (ADT) or anti-androgens for the treatment of hormone-naïve PCa." (PMID 27472325, 2016). "Recently, a function of the androgen receptor (AR) in the radiation response of prostate tumor cells was elucidated." (PMID 26784176, 2016). "Prostate cancer noncoding RNA 1 (PRNCR1; PCAT- 8), which was identified to be upregulated in aggressive prostate tumors, promotes AR methylation at K 349 and results in ligand-independent activation of AR signaling and cell proliferation." (PMID 27191265, 2016). "The combination of AR blockage and GR-mediated transrepression resulted in an inhibition of prostate tumor growth in vitro and bladder cancer cell xenograft growth in vivo." (PMID 27713909, 2016). "On the other hand, prostate tumors that have received prolonged androgen receptor (AR)-blocking anti-androgen therapy (e.g. enzalutamide) display a relatively higher GR expression level which rather increases cell viability and facilitates progression in vivo." (PMID 27713909, 2016). "To further study the link between KLF4 and its targets AR and miR-1 in clinical samples, we analyzed 22 independent prostate tumor tissue samples collected from the Wan Fang Hospital, Taipei Medical University (Taiwan)." (PMID 27991915, 2016). "Specifically, we built a heterologous AR expression system into LNCaP human prostate tumor cells to identify AR-interacting proteins using quantitative mass spectrometry." (PMID 27365400, 2016). "Nonetheless, the siRNA-based transcriptional screen revealed that the expression of ligand-sensitive proteins was required for optimal AR transcriptional activity in LNCaP prostate tumor cells." (PMID 27365400, 2016). "Of note, myosin VI (MYO6) is a minus-end-directed motor protein that binds AR, regulates AR stability, and modulates AR-dependent transcription in prostate tumor cells." (PMID 27365400, 2016). "In sum, PHF8 and AR were confirmed to be co-expressed in human PCa samples, mouse prostate, and mouse prostate tumors, supporting our cell line-based findings that AR positively regulates PHF8." (PMID 27689328, 2016). "For example, the proteasome system has an active role in androgen-dependent AR transcription, AR trafficking, and AR metabolism in prostate tumor cells." (PMID 27365400, 2016). "We also targeted components of the ubiquitination/SUMOylation pathways because these enzymes strongly affect AR metabolism and function in prostate tumor cells." (PMID 27365400, 2016). "Overall, these results showed that SBP-AR undergoes ligand-dependent cytoplasmic-nuclear translocation, is transcriptionally activated by androgens in N-AR cells, and phenocopies AR-T877A functions in prostate tumor cells." (PMID 27365400, 2016). "These IF results validate previous studies showing that unliganded AR is primarily cytosolic in prostate tumor cells." (PMID 27365400, 2016). "Together, these data suggest that ARD1-mediated AR acetylation at K618 plays a critical role in prostate tumor growth." (PMID 27659526, 2016). "Overall, the bioinformatic analyses demonstrated that the proteomic screen enriched for the AR-interactome and molecular pathways related to AR function in prostate tumor cells." (PMID 27365400, 2016). "The AR response is ubiquitous in prostate tumors, and NKX3.1 is upregulated by androgens; in contrast, NKX3.1 loss has been reported in prostate tumors." (PMID 25705129, 2015). "Studies using cell lines and human prostate tumor samples confirmed the underexpression of miR-99a in PC, and showed that the reduction in miR-99a provides a growth advantage for AR-positive PC cells under an androgen-depleted condition." (PMID 26690121, 2015). "YB-1 is known to be upregulated during prostate tumor progression, and promotes AR transcription via binding to the Y-box in the AR promoter region." (PMID 26314494, 2015).
prostate tumors (continued). "AR activation by CDK5 phosphorylation has been identified as a cancer-driving mechanism in prostate tumors." (PMID 26509276, 2015). "Frequent AR positivity is found in more highly differentiated versus poorly differentiated tumors; further, AR was rarely seen in prostate tumors of patients who had received long-standing hormonal therapy [S61]." (PMID 25595907, 2015). "The present study demonstrated that sulfur significantly inhibited AR expression in 22Rv1 prostate tumors." (PMID 25436005, 2015). "A previous study showed that YB-1 is upregulated during prostate tumor progression, and it promotes AR transcription via binding to the Y-box in the AR promoter region." (PMID 26314494, 2015). "Based on our results, we assume that this therapy would prevent an AR-mediated decrease of MB transcripts, thereby indirectly ensuring higher levels of MB expression in prostate tumor cells." (PMID 26559958, 2015). "GPR158 expression was increased at the invading front of prostate tumors that formed in the genetically defined conditional Pten knockout mouse model, and co-localized with elevated AR expression in the cell nucleus." (PMID 25693195, 2015). "In prostate, SPDEF directly interacts with the androgen receptor functioning as a co-activator to induce prostate-specific antigen (PSA) in LNCaP prostate tumor cells." (PMID 25254494, 2014). "Here we show for the first time that both enzalutamide and abiraterone render prostate tumor cells more sensitive to T cell-mediated lysis through immunogenic modulation, and that these immunomodulatory activities are androgen receptor (AR)-dependent." (PMID 25344864, 2014). "Here, we show that enzalutamide enhances sensitivity to immune-mediated killing of prostate tumor cells that overexpress AR." (PMID 25344864, 2014). "We showed, in xenograft models, that PPD prevents or delays the development of CRPC after androgen deprivation and inhibits the growth of castration-resistant prostate tumors with endogenous expression of AR-FL and AR-Vs." (PMID 25375370, 2014). "The deregulated androgen receptor signaling is undeniably most important in the progression of the majority of prostate tumors." (PMID 25277175, 2014). "Our results suggest that combining GSK-3, AR and NFκB inhibitors will provide a more effective therapy than single agents for the treatment of some prostate tumors." (PMID 25327559, 2014). "Factors influencing differential responses of prostate tumors to androgen receptor (AR) axis-directed therapeutics are poorly understood, and predictors of treatment efficacy are needed." (PMID 25356728, 2014). "AR, and more widely the androgens signalling, is one of the main pathways that support prostatic tumours growth and metastatic dissemination." (PMID 24796332, 2014). "As expected, we observed reduced tumour volume of AR silenced TRAMP-C1 tumours (scr vehicle vs. siAR vehicle, p < 0.001), confirming the AR function is essential for prostate tumour growth." (PMID 23982944, 2013). "In summary, our results show that combined treatment of prostate tumors with antisense oligonucleotides targeting AR and PKARIα is more effective than single treatments in androgen-sensitive LNCaP and castration-resistant LNCaPabl tumors." (PMID 23736698, 2013). "In particular, for patient #9, the prostate tumor showed AR copy number increase, whereas the metastatic lesions all had average AR <2." (PMID 24098661, 2013). "Here we examined the effects of ganetespib in a panel of prostate tumor lines and in both AR-dependent and independent xenograft models." (PMID 23152004, 2013). "Several preclinical studies have revealed that inhibiting AR expression by itself through small antisense molecules is effective in inhibiting prostate tumor growth." (PMID 23736698, 2013). "RB is a master cell cycle regulator and key component of the proliferative response to AR which is lost or inactivated with high frequency (30–60%) in prostatic neoplasms." (PMID 23152004, 2013).
prostate tumors (continued). "SirT1 has also been shown to inhibit androgen receptor-dependent cell proliferation in prostate tumor cells." (PMID 24223900, 2013). "In the analyses of AR, 3 (#3, #9, and #11) out of 10 patients (30%) showed results in the prostate that deviated from extra-prostatic tumors." (PMID 24098661, 2013). "The efficacy of the HSP90 inhibitors were then assessed in cells transfected with a range of somatic missense gain-of-function AR point mutants that have been previously identified in clinical prostate tumors, mouse models, xenografts and cell lines." (PMID 23674566, 2013). "As a result, ETS genes become coupled to androgen receptor (AR) signaling and are overexpressed in fusion-positive prostate tumors." (PMID 23555854, 2013). "Two out of nine WT/TRAMP mice displayed metastasis in lung and lymph nodes (LN), but eight out of nine MARKO/TRAMP mice had metastasis, suggesting that the ablation of AR in macrophages favours the development of metastatic prostate tumours in TRAMP mice." (PMID 23982944, 2013). "Our study provides rationale for targeting Akt, EGFR, Src, Bcl-2, and AR signaling as a treatment for AR-positive relapsed prostate tumors after hormone therapy." (PMID 24349321, 2013). "Most castration-resistant prostate tumors continue to express the androgen receptor (AR) as well as androgen-responsive genes, despite the near absence of circulating androgen in these patients." (PMID 22761715, 2012). "The androgen receptor (AR) is active in the majority of prostate tumors which enabled the generation of adenoviral mutants with replication controlled by AR response elements (AREs) to prevent replication in non-prostate tissue." (PMID 23056370, 2012). "Our studies suggest that let-7c suppresses prostate tumor growth by several pathways including regulation of IL-6, Myc, Lin28 and the AR." (PMID 22479342, 2012). "The AR is a key survival factor for prostate tumor cells and reduction of its expression has been demonstrated to suppress prostate tumor growth." (PMID 22479342, 2012). "B-DIM also activates AMPK and down-regulates AR in androgen-independent C4-2B prostate tumor xenografts in SCID mice." (PMID 23056607, 2012). "Such a positive-feedback loop is most likely to lead to constant activation of the AR, which at least partially explains the epidemiologic observation that a high concentration of testosterone level correlates with a high incidence of prostate tumor." (PMID 22194926, 2011). "Androgens, including testosterone (T) and its active metabolite 5α-dihydrotestosterone (5α-DHT), are important for the development and growth of early stage prostate tumors and exert their effects via androgen receptor (AR)." (PMID 21592394, 2011). "A reduction in the level of circulating androgens results in apoptosis of the AR-expressing luminal epithelial cells, normally leading to initial prostate tumour regression." (PMID 20585617, 2010). "We previously demonstrated that Ack1 regulates phosphorylation of androgen receptor and tumor suppressor Wwox in human prostate tumors." (PMID 20333297, 2010). "A large number of androgen-refractory prostate tumours retain AR expression, indicating potential activation of AR even in the absence of androgens." (PMID 19888222, 2009). "In another study, Ebp1 overexpression resulted in downregulation of the androgen receptor leading to reduced incidence of androgen-dependent prostate tumours and slower tumour growth." (PMID 19367286, 2009). "Prostate tumour growth is almost always dependent upon the androgen receptor pathway and hence therapies aimed at blocking this signalling axis are useful tools in the management of this disease." (PMID 19721807, 2009). "Fifth, for prostate tumors, withaferin A was able to sensitize androgen receptor (AR)-positive PC-3 prostate tumor cell line to androgen ablation therapy via the prostate apoptosis response-4 (Par-4) gene." (PMID 18348714, 2008).
prostate tumors (continued). "A majority of prostate tumors obtained from patients failing androgen ablation therapy overexpress the androgen receptor (AR), sensitizing the cells to low levels of androgen." (PMID 18288312, 2008). "Even more striking, aberrant AR activity seems to be necessary and sufficient to convert androgen-dependent prostate tumors to ablation resistant ones; this fact has made the AR an attractive target for PCa therapy." (PMID 18997859, 2008). "The specific alternative signaling pathways that allow prostate tumors to bypass AR have been somewhat elusive, one candidate pathway possibly involving BCL2." (PMID 17598908, 2007). "Prostate tumor cells can escape androgen-ablation therapies by multiple mechanisms involving the androgen receptor." (PMID 17925854, 2007). "Rescue experiments are inadequate here, because even a modest increase in AR expression modifies the phenotype of the prostate tumor cells." (PMID 17925854, 2007). "Nearly 44% (23/52, sample ID labeled in red) of the prostate tumors showed the 'dasatinib-responsive' expression patterns (that is, low AR and PSA and high uPA, EphA2 and/or CK5)." (PMID 18047674, 2007). "Our results demonstrate that androgen dependent, but also and more importantly, exponentially growing and vascularized castration-resistant prostate tumors, are still dependent on the expression of a functional AR for their growth and angiogenesis." (PMID 17925854, 2007). "Our findings reveal that monocyte-derived IL-1beta inhibits the proliferation of androgen-responsive prostate tumour cells and reduces AR and PSA levels." (PMID 9792142, 1998). "In addition to the ATAC-seq peaks, we included AR ChIP-seq peaks in human prostate tumor tissues retrieved from a publicly available dataset (GSE56288) and ChIP-seq peaks for TFs associated with PCa in the GTRD database." (PMID 40525903, 2025). "Furthermore, CDC25B, a cell cycle phosphatase frequently overexpressed in high-grade prostate tumors, has been shown to act as a co-activator of the androgen receptor (AR), thereby promoting AR-mediated transcription even under androgen-deprived conditions." (PMID 40491606, 2025). "In contrast to well-documented mechanisms of adaptive resistance involving AR point mutations or amplification after long-term exposure to ADT, a subset of aggressive prostate tumors displays resistance to ADT as measured by transcriptional profiling of the tumor to have lower AR activity." (PMID 40906535, 2025). "The literature suggests that aggressive prostate tumors frequently demonstrate dysregulation of androgen receptor (AR) signaling, alterations in ETS transcription factors due to TMPRSS2-ERG fusion events, and overexpression of clinically monitored biomarkers such as PCA3." (PMID 41375053, 2025). "Furthermore, AR overexpression in prostate tumors from diabetic individuals suggests that metabolic stress augments hormone sensitivity and metastatic potential." (PMID 41139205, 2025). "However, as we have shown here, a feature of prostate tumors to resist direct AR antagonism by enzalutamide is their intrinsic phenotype of having lower levels of AR activity." (PMID 40906535, 2025). "Likewise, the TMPRSS2:ERG gene fusion, commonly assessed in platforms like MiPS, arises from AR-driven transcriptional activity and reshapes the transcriptomic landscape of prostate tumors." (PMID 40649790, 2025). "The androgen receptor (AR) pathway remains central to prostate tumor biology." (PMID 40565559, 2025). "The NSD2 subunit is essential for AR/FOXA1 neo-enhancer-driven prostate tumors." (PMID 40290121, 2025). "Future work will examine how AR and its signaling exhibits the cell-specific effects within prostate tumors and how this affects interactions between cancer cells and immune cells in the tumor microenvironment to produce differential responses to AR-targeted therapies." (PMID 38820127, 2024).
prostate tumors (continued). "Thus, the ‘epigenetic switch’ from pY54-H3 to pY88-H4 at the AR locus determines expression of the AR global transcriptome, driving prostate tumor growth." (PMID 38965223, 2024). "In this setting, patients with AR-high tumors had worse outcomes when considering all prostate tumor biopsies (HR = 2.0, 95% CI = 1.7–2.3, P value < 0.0001) or bone (HR = 2.6, 95% CI = 1.8–3.6, P value < 0.0001) and lymph node metastasis (HR = 2.1, 95% CI = 1.6–2.7, P value < 0.0001)." (PMID 39207857, 2024). "This cell line was chosen to accurately replicate the effects of the PPAT-EVs within a relevant biological context, as all our PPAT samples originate from androgen-sensitive tumours, and 22Rv1 cells derive from a primary prostate tumour and possess the androgen receptor." (PMID 39010137, 2024). "Thus, ADT, directly targeting AR-expressing prostate tumor cells, has been the main, and also initially effective treatment for advanced PCa." (PMID 39369165, 2024). "Prostate tumors with higher AR expression level correlated with worse clinical outcome." (PMID 39149855, 2024). "MA abrogated AR biogenesis and inhibited prostate tumor growth in mice." (PMID 38605607, 2024). "However, the number and kind of AR-co-regulators and AR-responsive genes in different normal and cancerous tissues, particularly in cancers other than prostatic tumors, and the impact of the level of AR are still the subjects of current research." (PMID 38790919, 2024). "Interestingly, RhoA, which is an androgen receptor targeted gene, has also been shown to be dysregulated and overexpressed in AA prostate tumors." (PMID 38785827, 2024). "Some studies suggest that AR targeting therapies may increase numbers of infiltrating immune cells in prostate tumours, although reports on this are conflicting." (PMID 38448753, 2024). "Moreover, GLI3 interacts with AR to enrich AR-dependent gene expression, leading to the castration-resistant growth of prostate tumours." (PMID 38126976, 2023). "Androgen receptor (AR) knockout mice showed higher incidence of metastatic prostate tumors and higher corresponding levels of CCL2 while other studies have shown that AR knockout causes a significant increase in MMP9 which has been indicated for its role in cancer metastasis." (PMID 36836690, 2023). "CDK1 phosphorylates the AR at Ser81 or Ser515 promoting prostate tumor progression." (PMID 37311884, 2023). "Our data suggest MPC inhibition and lactate accumulation may make prostate tumours more resistant to androgen receptor inhibition." (PMID 38049604, 2023). "At diagnosis, most prostate tumours rely on androgen receptor signalling to promote proliferation." (PMID 38049604, 2023). "Using the IHC to evaluate the PSA expression in primary and metastatic tumors, our data demonstrated that PSA expression was decreased in higher Gleason grade tumors, which is consistent with observations that during aggressive cancer growth, prostate tumors lower dependency on AR regulation." (PMID 36765916, 2023). "In this respect, further studies of the epigenetic actions of the AR antagonists are necessary to improve the understanding of the molecular mechanism of the transition from a hormone-dependent to hormone-resistant state in prostatic tumors." (PMID 37025180, 2023). "Further, ACK1 also phosphorylates ATP synthase F1 subunit α (ATP5F1A) in CRPC,126 and (R)-9b treatment not only significantly compromised AR transcriptional activity, but also mitigated increased mitochondrial energy output in cancer, diminishing prostate tumor growth." (PMID 37738978, 2023). "Moreover, studies have shown a correlation between the expression levels of enzymes facilitating AR function in prostatic tumors and the malignancy of the tumor." (PMID 37025180, 2023). "SELENBP1 is found to coprecipitate with the androgen receptor (AR) in prostate tumor cells." (PMID 36386843, 2022). "Many human castration-resistant prostate tumors retain expression of AR." (PMID 36175875, 2022).